NIPBL (NIPBL cohesin loading factor)
Description:
Plays an important role in the loading of the cohesin complex on to DNA. Forms a heterodimeric complex (also known as cohesin loading complex) with MAU2/SCC4 which mediates the loading of the cohesin complex onto chromatin. Plays a role in cohesin loading at sites of DNA damage. Its recruitment to double-strand breaks (DSBs) sites occurs in a CBX3-, RNF8- and RNF168-dependent manner whereas its recruitment to UV irradiation-induced DNA damage sites occurs in a ATM-, ATR-, RNF8- and RNF168-dependent manner. Along with ZNF609, promotes cortical neuron migration during brain development by regulating the transcription of crucial genes in this process. Preferentially binds promoters containing paused RNA polymerase II. Up-regulates the expression of SEMA3A, NRP1, PLXND1 and GABBR2 genes, among others (By similarity).
Synonyms: IDN3; SCC2; DKFZp434L1319; FLJ11203; FLJ12597; FLJ13354; FLJ13648; CDLS; CDLS1; IDN3-B
Tractability: Small molecule: a structure with a bound ligand is known. PROTAC: ubiquitination databases record sites on it; its protein half-life has been measured.
Gene: Protein-coding gene on chromosome 5 (36,876,769 to 37,066,413, forward strand). Ensembl gene ENSG00000164190.
Subcellular location: Nucleus; Chromosome
Subcellular location (Human Protein Atlas): Nucleoplasm; Cytosol; Vesicles
Pathways (Reactome):
Cell Cycle: Cohesin Loading onto Chromatin
Gene Ontology:
Molecular function: chromo shadow domain binding; cohesin loader activity; histone deacetylase binding; protein binding; transcription corepressor activity; chromatin binding; promoter-specific chromatin binding; mediator complex binding
Biological process: brain development; cellular response to X-ray; chromatin remodeling; cognition; developmental growth; DNA damage response; ear morphogenesis; embryonic digestive tract morphogenesis; embryonic forelimb morphogenesis; external genitalia morphogenesis; eye morphogenesis; face morphogenesis; forelimb morphogenesis; gallbladder development; heart morphogenesis; intracellular protein localization; maintenance of mitotic sister chromatid cohesion; mitotic sister chromatid cohesion; negative regulation of transcription by RNA polymerase II; outflow tract morphogenesis; regulation of developmental growth; regulation of embryonic development; regulation of hair cycle; sensory perception of sound; uterus morphogenesis; and 13 more
Cellular component: extracellular exosome; nucleoplasm; nucleus; Scc2-Scc4 cohesin loading complex; SMC loading complex; chromosome; integrator complex; chromatin
Genetic constraint (gnomAD): Loss-of-function variants: 7 observed, 229.94 expected, observed/expected ratio (o/e) 0.0304, 90% interval 0.016 to 0.057. The upper end of that interval is the gene's LOEUF score, 0.057, which puts it in group 1 of 6, group 1 being the genes least tolerant of losing a copy. Missense variants: 1,814 observed, 2,781.4 expected, observed/expected ratio (o/e) 0.65, 90% interval 0.63 to 0.68. Synonymous variants: 915 observed, 954.9 expected, observed/expected ratio (o/e) 0.96, 90% interval 0.91 to 1.01.
Gene-disease validity (ClinGen):
ClinGen rates the evidence that NIPBL causes each of these diseases.
Cornelia de Lange syndrome (autosomal dominant): Definitive. A rare syndrome characterized by low birth weight, delayed growth, intellectual disabillity, behavioral problems, and a distinctive facial appearance (thin, arched eyebrows, low set ears, small teeth, and small nose).
Homologues: Orthologues: chimpanzee NIPBL (99% identical), macaque NIPBL (99% identical), dog NIPBL (98% identical), pig NIPBL (98% identical), mouse Nipbl (97% identical), rat Nipbl (96% identical), guinea pig NIPBL (93% identical), rabbit NIPBL (90% identical), tropical clawed frog nipbl (82% identical), zebrafish nipblb (68% identical), zebrafish nipbla (60% identical), Drosophila melanogaster Nipped-B (27% identical), and 1 more.
Diseases named in the same sentence as NIPBL in open-access papers:
NIPBL is named in the same sentence as 84 diseases in open-access papers, as found by Europe PMC text mining. Sharing a sentence is not in itself a finding about the gene and the disease. The quoted sentences say what the papers report.
Cornelia de Lange syndrome (133 papers, 2008 to 2026). "The NIPBL gene, which encodes the cohesin loader Nipped-B–like protein, is the most frequently mutated gene in Cornelia de Lange syndrome (CdLS), a severe autosomal dominant cohesinopathy." (PMID 41338928, 2026). "For example, a patient with a NIPBL mutation (Cornelia de Lange syndrome) presented with synophrys, long curly eyelashes, a depressed nasal bridge, and a thin upper lip, along with vesicoureteral reflux." (PMID 41300846, 2025). "The most common cohesinopathy, Cornelia de Lange syndrome, is caused by dysfunction in a variety of cohesin subunits, such as NIPBL, SMC1A, SMC3, RAD21, BRD4, HDAC8, and ANKRD11." (PMID 40943870, 2025). "Currently, there is only one case, demonstrates the correlation between this novel intronic variant of NIPBL gene and Cornelia de Lange syndrome." (PMID 41000420, 2025). "This so-called “loop extrusion” function of cohesin is dependent on NIPBL/Scc2, frequently mutated in Cornelia de Lange Syndrome (CdLS) patients." (PMID 38055079, 2024). "Intriguingly, BRD4 has been implicated in the neurodevelopmental disorder Cornelia de Lange Syndrome (CdLS), typically caused by mutations in the cohesion complex gene NIPBL." (PMID 38567724, 2024). "The genetic etiology of Cornelia de Lange syndrome (CdLS) is mainly attributed to variants affecting the cohesin complex, and more specifically to heterozygous variants in the NIPBL gene." (PMID 39553472, 2024). "In Cases 1 and 3 described, limb reduction abnormalities and the classic phenotype suggest a high likelihood of Cornelia de Lange syndrome, possibly related to mutations in the NIPBL gene." (PMID 38673696, 2024). "Cornelia de Lange syndrome (CdLS) is a developmental multisystem disorder frequently associated with mutations in NIPBL." (PMID 35476527, 2022). "On the other hand, NIPBL is a hallmark of the Cornelia de Lange syndrome, a disease exhibiting growth anomalies, facial dysmorphism, and cognitive retardation." (PMID 35353576, 2022). "The human ortholog of Drosophila Nip-B is NIPBL, whose heterozygous mutations account for about 60% of the cases of Cornelia de Lange syndrome (CdLS), a genetic disorder with multiple developmental abnormalities." (PMID 36231024, 2022). "Another pathogenic variant identified in the present study was in the NIPBL gene; this variant is associated with Cornelia de Lange syndrome." (PMID 34829455, 2021). "The major causative genes of the Cornelia de Lange Syndrome are NIPBL, SMC1A, SMC3, RAD21 and HDAC8." (PMID 34827619, 2021). "Perturbation of the cohesin loading factor NIPBL in both mouse and zebrafish results in multi-organ defects (including heart abnormalities) reminiscent to the Cornelia de Lange Syndrome, a congenital disease linked to NIPBL mutation." (PMID 33777110, 2021). "Cornelia de Lange syndrome, which is caused by loss-of-function mutations of the NIPBL gene on 5p13, is also known to include CDH." (PMID 33750440, 2021). "Germline mutations in genes encoding the cohesin loader NIPBL, or in cohesin subunits, cause a spectrum of human developmental disorders, the best known of which is Cornelia de Lange Syndrome (CdLS)." (PMID 33365313, 2020). "Cornelia de Lange syndrome (CdLS), the best characterized cohesinopathy, is caused by mutations of cohesin regulators, such as NIPBL and HDAC8, or of cohesin subunits, including SMC1A, SMC3, and RAD21." (PMID 33262685, 2020). "Cornelia de Lange syndrome (CdLS) results from autosomal dominant or X-linked mutations in NIPBL, SMC1A, SMC3, RAD21 or HDAC8." (PMID 31935221, 2020). "Missense and protein-truncating mutations in NIPBL have been reported to cause Cornelia de Lange syndrome." (PMID 31906059, 2019). "NIPBL mutations are associated with Cornelia de Lange syndrome, with features that include growth retardation, a distinct facial phenotype, hirsutism, upper extremity malformations, cardiac defects, and mental retardation." (PMID 29368431, 2018).
Cornelia de Lange syndrome (continued). "Heterozygous pathological variants in the NIPBL gene are the main cause of Cornelia de Lange syndrome, the most frequent cohesinopathy." (PMID 28241484, 2017). "Mutations in NIPBL are the most frequent cause of Cornelia de Lange syndrome (CdLS), a developmental disorder encompassing several neurological defects, including intellectual disability and seizures." (PMID 28041881, 2017). "A single NIPBL missense mutation, derived from a Cornelia de Lange Syndrome (CdLS) patient, prevents a 300-amino-acid NIPBL fragment from binding MAU2." (PMID 28167679, 2017). "This study provides insight into the molecular pathology of Cornelia de Lange syndrome by establishing a relationship between NIPBL and HDAC8 mutations and PKR activation." (PMID 26725122, 2016). "In a paper published in this issue, Santos and colleagues describe studies of Cornelia de Lange syndrome-associated secundum atrial septal defects (ASDs) caused by NIPBL mutations, undertaken with a targeted trapping allele in mice." (PMID 27606622, 2016). "HP1α also strongly interacts with NIPBL, which is mutated in individuals with Cornelia de Lange syndrome." (PMID 26739615, 2016). "Chromosomes of an individual with Cornelia de Lange Syndrome and a mutation in NIPBL, another cohesin gene, exhibited apparently normal morphology." (PMID 26273322, 2015). "Cohesin's binding to chromatin depends on NIPBL, a factor that was found to be mutated in 50% of the cases of the human developmental disorder Cornelia de Lange Syndrome (CdLS)." (PMID 24550742, 2014). "Mutations in NIPBL and cohesin subunits, have been linked to the “Cohesinopathy” Cornelia de Lange syndrome (CdLS, OMIM #122470, #300590 and #610759)." (PMID 24550742, 2014). "Mutations in human NIPBL and genes encoding cohesin subunits cause a developmental disorder called Cornelia de Lange syndrome." (PMID 23967866, 2013). "Cornelia de Lange syndrome (CdLS) is a developmental disorder caused by mutations in NIPBL, a protein which has functionally been associated with the cohesin complex." (PMID 23760082, 2013). "Mutations in NIPBL result in Cornelia de Lange syndrome (MIM ID# 122470), a disorder characterized by dysmorphic facial features, growth delay, limb reduction defects as well as intellectual disability." (PMID 23227143, 2012). "Heterozygous mutations in Smc1, Smc3 and Scc2/Nipped-B/NIPBL have been associated with the human disease Cornelia de Lange syndrome (CdLS)." (PMID 22719263, 2012). "Inactivating mutations in NIPBL are associated with Cornelia de Lange syndrome and one of the characteristic features of this syndrome is reduction in limb growth (OMIM 122470)." (PMID 21235737, 2011). "Haploinsufficiency for NIPBL is the most frequent cause of Cornelia de Lange Syndrome (CdLS) (OMIM #122470), the most common of the cohesinopathies." (PMID 22039349, 2011). "Cornelia de Lange Syndrome (CdLS), on the other hand, is caused by haploinsufficiency for NIPBL or by missense mutations in the SMC1A or SMC3 cohesin subunits." (PMID 21637801, 2011). "Hypomorphic mutations in the cohesin subunits SMC1 and SMC3 and in the cohesin loading factor NIPBL have been identified as the molecular cause of Cornelia de Lange syndrome, a rare human developmental disorder." (PMID 19956766, 2009). "Cornelia de Lange Syndrome (CdLS) is a multi-organ system birth defects disorder linked, in at least half of cases, to heterozygous mutations in the NIPBL gene." (PMID 19763162, 2009). "Furthermore, they found evidence of a similar increase in DNA damage signalling in cells derived from individuals with NIPBL deficiency, suggesting that this is also a feature of typical Cornelia de Lange syndrome." (PMID 41300558, 2025). "Loss-of-function variants in NIPBL cause Cornelia de Lange syndrome; missense variants in ACTG1 lead to Baraitser-Winter syndrome; missense variants in ATP1A3 underlie Snijders Blok-Campeau syndrome; and loss-of-function variants in TCF4 result in Pitt-Hopkins syndrome." (PMID 41300846, 2025).
Cornelia de Lange syndrome (continued). "While some cases can be attributed to single-gene syndromes (e.g., NIPBL-associated Cornelia de Lange Syndrome), others may result from multiple co-occurring syndromes." (PMID 41510282, 2025). "In addition, heterozygous mutations in subunits of the cohesin complex (SMC1, SMC3, RAD21) or its chromatin loader (NIPBL) cause Cornelia de Lange syndrome (CdLS) which also frequently manifests as intellectual disability and neurodevelopmental delay." (PMID 39988079, 2025). "Mutations in MAU2 and NIPBL, the human cohesin loader subunits, are the cause of Cornelia de Lange Syndrome (CdLS), a hereditary disorder whose clinical features are thought to be the consequence of subtle gene expression changes in numerous developmental genes." (PMID 36509793, 2022). "Furthermore, we find evidence of a similar increase in DNA damage signalling in cells derived from NIPBL-deficient individuals, suggesting that defective DNA damage signalling and repair is also a feature of typical Cornelia de Lange syndrome." (PMID 34035299, 2021). "Furthermore, mutations in NIPBL are the cause of Cornelia de Lange syndrome, a congenital disorder whose clinical features are thought to be the collective outcome of gene expression changes during development." (PMID 30922844, 2019). "In 120 Cornelia de Lange syndrome patients, about 47% (56/120) of all cases showed NIPBL mutations." (PMID 30713220, 2019). "We hypothesize that translational dysfunction may contribute to the human disorder Cornelia de Lange syndrome, which is caused by mutations in NIPBL, the human ortholog of SCC2." (PMID 26176819, 2015). "The remaining case loss-of-function de novo mutations include some Mendelian disease genes with an existing neurological association, such as NIPBL, which is known to cause Cornelia de Lange syndrome and KMT2A, which is known to cause Wiedemann-Steiner Syndrome." (PMID 26332131, 2015). "If so, this could underlie many of the development deficits seen in Cornelia de Lange syndrome, caused by mutations in NIPBL and cohesin subunit genes." (PMID 23979932, 2013). "Mutations in the complex and its loading factor, NIPBL, have been identified in developmental disorders such as Cornelia de Lange syndrome (CdLS), as well as in pediatric cancers, including acute lymphoblastic leukemia (ALL) and Ewing sarcoma." (PMID 40867243, 2025). "Pathogenic variants in the NIPBL gene account for most cases of the rare developmental disorder, Cornelia de Lange syndrome (CDLS) (OMIM #122470)." (PMID 41155467, 2025). "Haploinsufficiency of NIPBL due to mutations accounts for approximately 70% of cases of Cornelia de Lange syndrome (CdLS), an inheritable disorder predominantly associated with cardiac septal defects." (PMID 39585787, 2024). "Surprisingly, DNA methylation analyses revealed a DNA methylation profile similar to the Cornelia de Lange syndromes 1–4 (CdLS) episignature, associated with variants in NIPBL, SMC1A, SMC3, and RAD21." (PMID 38273166, 2024). "Cornelia de Lange syndrome (CdLS) is a rare multisystem genetic disorder which is caused by genetic defects involving the Nipped-B-like protein (NIPBL) gene in the majority of clinical cases (60–70%)." (PMID 36056433, 2022). "Future studies that explore this relationship between cohesin loading and the PTIP/PA1 complex could provide insights into not just cohesin dynamics and function but also the developmental disease Cornelia de Lange Syndrome which is often characterized by heterozygous mutations in NIPBL." (PMID 34462321, 2021). "Interestingly, mutations in the NIPBL gene are responsible for Cornelia de Lange syndrome, a multisystem congenital disorder that is characterized by dysmorphic facial features, growth retardation, gastroesophageal dysfunction, cardiac, and ocular anomalies, like glaucoma." (PMID 34348663, 2021).
Cornelia de Lange syndrome (continued). "Importantly, the realization that mutants in the cohesin loading subunit NIPBL cause Cornelia de Lange Syndrome (CdLS), a developmental disorder resulting in severe malformations and mental retardation, led to the discovery of a class of human genetic diseases known as cohesinopathies." (PMID 33836947, 2021). "Cornelia de Lange syndrome (CdLS), a rare, multisystemic disorder, has been linked to genetic alterations in NIPBL, SMC1A, SMC3, HDAC8, and RAD21 genes." (PMID 30606125, 2019). "Its functions critically depend on NIPBL, the cohesin-loader protein that is found to be mutated in >60% of the cases of Cornelia de Lange syndrome (CdLS)." (PMID 29261648, 2017). "Cornelia de Lange syndrome (CdLS) is a multisystem developmental disorder frequently associated with heterozygous loss-of-function mutations of Nipped-B-like (NIPBL), the human homolog of Drosophila Nipped-B." (PMID 28855971, 2017). "Mutations in NIPBL have been identified in approximately 60% of individuals with Cornelia de Lange syndrome (CdLS)." (PMID 25963978, 2015). "In metazoans, cohesin deposition by Scc2/4 is required for normal development, and mutations in NIPBL, the human homolog of Scc2, are dominant and causally linked to a severe developmental disorder, Cornelia de Lange Syndrome (CDLS)." (PMID 26038942, 2015). "Our observations reveal a dual role for NIPBL in cohesin loading and as potential transcription co-factor, which yields novel insights into how NIPBL defects could cause Cornelia de Lange Syndrome since NIPBL mutations might directly influence developmentally important genes." (PMID 24550742, 2014). "Heterozygous mutations of NIPBL were found in 50% of the cases of Cornelia de Lange Syndrome (CdLS), a human developmental syndrome with a complex phenotype." (PMID 24550742, 2014). "In humans, dominant loss-of-function mutations in the NIPBL gene encoding a kollerin subunit, and dominant missense mutations in the Smc1 or Smc3 cohesin subunits cause Cornelia de Lange syndrome (CdLS)." (PMID 23818863, 2013). "In Cornelia de Lange Syndrome (CdLS), partial deficiency for NIPBL, which encodes a cohesin regulator, is associated with small changes in the expression of many genes (similar effects are seen in Nipbl-deficient mice and flies)." (PMID 22039349, 2011). "Growth retardation, craniofacial anomalies, microbrachycephaly and reduced body fat have been described in cohesinopathies such as Cornelia de Lange syndrome CdLS, which is inherited in an autosomal dominant (NIPBL, SMC2 or RAD21) or X‐linked (SMC1A or HDAC8) pattern." (PMID 36627765, 2023). "For instance, Cornelia de Lange syndrome often associates with CDH, and its most common cause is mutations in the NIPBL gene on 5p13.2." (PMID 36261840, 2022). "Cornelia de Lange syndrome, also called Brachmann de Lange syndrome, is caused by heterozygous variants in NIBL gene at chromosome 5p13.1, encoding for the NIPBL protein." (PMID 34198563, 2021). "A duplication on chromosome 5, including the NIPBL gene region, has been reported to occur in Cornelia de Lange syndrome." (PMID 33750440, 2021). "Cornelia de Lange syndrome (CdLS) is the most prominent cohesinopathy and arises from heterozygous mutations, usually in the gene encoding cohesin regulator NIPBL, but sometimes in genes encoding the core mitotic-specific subunits of cohesin (RAD21, SMC3 and SMC1A) and the SMC3 deacetylase HDCA8." (PMID 34202641, 2021). "Mutations in NIPBL, the human ortholog of the Scc2 cohesin loader subunit, are the cause of Cornelia de Lange Syndrome (CdLS), a hereditary disorder whose clinical features are thought to be caused by the misregulation of gene expression programs during development." (PMID 32277274, 2020). "Mutations in NIPBL are the major cause of Cornelia de Lange Syndrome (CdLS)." (PMID 31320616, 2019).